FARP2 (FERM, ARH/RhoGEF and pleckstrin domain protein 2)
Description:
Functions as a guanine nucleotide exchange factor that activates RAC1. May have relatively low activity. Plays a role in the response to class 3 semaphorins and remodeling of the actin cytoskeleton. Plays a role in TNFSF11-mediated osteoclast differentiation, especially in podosome rearrangement and reorganization of the actin cytoskeleton. Regulates the activation of ITGB3, integrin signaling and cell adhesion (By similarity).
Synonyms: FIR; KIAA0793; PLEKHC3; FRG
Tractability: PROTAC: ubiquitination databases record sites on it; its protein half-life has been measured.
Gene: Protein-coding gene on chromosome 2 (241,356,264 to 241,494,847, forward strand). Ensembl gene ENSG00000006607.
Subcellular location (Human Protein Atlas): Cytosol
Pathways (Reactome):
Cell-Cell communication: SRC activates STAT3 in a quantitative manner, through Cadherin-11 (CDH11), RAC1 and gp130 (IL6ST)
Developmental Biology: SEMA3A-Plexin repulsion signaling by inhibiting Integrin adhesion
Signal Transduction: RAC1 GTPase cycle
Gene Ontology:
Molecular function: guanyl-nucleotide exchange factor activity; cytoskeletal protein binding
Biological process: neuron remodeling; Rac protein signal transduction; actin cytoskeleton organization; cell adhesion; osteoclast differentiation; podosome assembly; regulation of integrin activation; semaphorin-plexin signaling pathway; cell development; signal transduction
Cellular component: cytoplasm; cytosol
Genetic constraint (gnomAD): Loss-of-function variants: 67 observed, 81.67 expected, observed/expected ratio (o/e) 0.82, 90% interval 0.67 to 1. The upper end of that interval is the gene's LOEUF score, 1, which puts it in group 4 of 6, group 1 being the genes least tolerant of losing a copy. Missense variants: 1,085 observed, 1,069.1 expected, observed/expected ratio (o/e) 1.01, 90% interval 0.96 to 1.07. Synonymous variants: 420 observed, 430.37 expected, observed/expected ratio (o/e) 0.98, 90% interval 0.9 to 1.06.
Homologues: Orthologues: chimpanzee FARP2 (98% identical), macaque FARP2 (97% identical), guinea pig FARP2 (84% identical), mouse Farp2 (84% identical), rat Farp2 (82% identical), rabbit FARP2 (76% identical), dog FARP2 (75% identical), pig FARP2 (67% identical), zebrafish farp2 (66% identical), tropical clawed frog FARP2 (30% identical), Caenorhabditis elegans frm-3 (27% identical), Caenorhabditis elegans exc-5 (14% identical). Paralogues in human: FARP1 (54% identical), FRMD7 (23% identical), FGD6 (19% identical), FGD5 (19% identical), FGD1 (17% identical), FGD4 (16% identical), FGD3 (14% identical), FGD2 (13% identical), ECT2L (11% identical), ARHGEF39 (7% identical).
Diseases named in the same sentence as FARP2 in open-access papers:
FARP2 is named in the same sentence as 15 diseases in open-access papers, as found by Europe PMC text mining. Sharing a sentence is not in itself a finding about the gene and the disease. The quoted sentences say what the papers report.
diabetes (2 papers, 2017 to 2019). "FARP2 was identified as a candidate gene in diabetes research, and is correlated with energy metabolism and obesity-associated pathologies." (PMID 28877683, 2017).
autism (1 paper, 2023). Persistent deficits in social interaction and communication and interaction as well as a markedly restricted repertoire of activity and interest as well as repetitive patterns of behavior. "Contrary to other studies where a haploinsufficiency of KIF1A, FARP2, HDLBP, and AGAP1 genes was cited as a possible cause for autism in 30–35% of 2q37DS, in our patients, autistic spectrum disorder was found in just one case." (PMID 36833393, 2023).
breast carcinoma (1 paper, 2026). "Pathway enrichment revealed associations with cell cycle regulation (E2F3, MKI67), DNA repair (BRCA2), and transcriptional control (MED1), with six priority genes (MED1, BRCA2, E2F3, PITPNB, H1-1, and FARP2) showing established breast cancer relevance." (PMID 41614924, 2026).
chronic lymphocytic leukemia (1 paper, 2021). "FARP2 has been reported as a potential regulator of chronic lymphocytic leukemia pathogenesis that influences protein activity encoded by MYC gene." (PMID 34373545, 2021).
pancreatic cancer (1 paper, 2022). "This included elements of the Hedgehog signaling pathway (SHH, GAS1), semaphorin signaling (SEMA3A, PLXNA1, PLXNB2, PLXND1, PLXNA2, FARP1, FARP2) and also axon guidance pathways (ROBO1, SLIT1, SLIT3 and SLITRK2), all notable for their involvement in pancreatic cancer progression and metastasis." (PMID 36429078, 2022).
prostate carcinoma (1 paper, 2015). A carcinoma that arises from epithelial cells of the prostate gland. "rs3771570, which is associated with aggressive prostate cancer, is located in the intronic region of FARP2 gene." (PMID 26496489, 2015).
cancer (2 papers, 2021 to 2023). A tumor composed of atypical neoplastic, often pleomorphic cells that invade other tissues. "Three nsSNPs; rs1126809 (TYR), rs10936600 (LRRC34), and rs757978 (FARP2), were found as the most damaging cancer pathogenic variants." (PMID 34373545, 2021). "The mutation in FARP2 might disrupt the formation of axonal and dendritic morphologies for the neurodevelopment that ultimately lead to risks of cancers." (PMID 34373545, 2021). "Gene FARP2 is involved in the Rho guanyl-nucleotide exchange factor activity and in the development and progression of cancer." (PMID 37844188, 2023). "As TYR, LRRC34, and FARP2 genes play important roles in numerous cellular processes such as cell proliferation, differentiation, growth, and cell survival; therefore, any impairment on the protein function could be involved in the development of cancer." (PMID 34373545, 2021). "Thus, the deviation observed in the bound SRC molecule with mutant FARP2 protein might disrupt the protein interaction, leading to cancers." (PMID 34373545, 2021).
FARP2 also shares sentences with these, for which no sentence is quoted: alcohol dependence (1 paper); autistic spectrum disorder (1); behavioral disorders (1); brachydactyly (1); ischemic stroke (1); neurodevelopmental disorder (1); Obesity (1); Parkinson disease (1).